BRCA2 (BRCA2 DNA repair associated)
Diseases named in the same sentence as BRCA2 in open-access papers (continued):
Sharing a sentence is not in itself a finding about the gene and the disease.
pancreatic cancer (continued). "Nevertheless, some studies implied that specific mutations, for example, the BRCA2 exon 11 mutation, increase the incidence of colorectal, stomach and pancreatic cancers more than other mutations." (PMID 34577828, 2021). "The association between pancreatic cancer and BRCA1 is well established, with up to 10% of familial pancreatic cancer being attributable to either a BRCA1 or BRCA2 variant." (PMID 35155181, 2021). "PALB2 (partner and localizer of BRCA2) is also involved in DNA damage repair and Fanconi anemia, which is strongly associated with breast, ovarian, and pancreatic cancer." (PMID 34476650, 2021). "Germline mutations in BRCA2 are associated with an increased risk for breast, ovarian, prostate, and pancreatic cancer." (PMID 34065235, 2021). "To evaluate the efficacy of the newly identified putative RAD52 inhibitors, we first treated patient-derived BRCA2-proficient (BxPC3) and BRCA2-deficient (Capan-1) pancreatic cancer cells." (PMID 33995041, 2021). "Genetic epidemiological evidence suggested that the BRCA2 c.9976A>T variant contributes to the risk of developing familial pancreatic cancer and lung cancer." (PMID 33672545, 2021). "A deleterious germline mutation in the PALB2 (Partner and Localizer of BRCA2) gene, which accounts for 3–4% of familial pancreatic cancer cases, was identified in a 53‐year‐old female patient." (PMID 33350171, 2021). "In a phase II trials of olaparib and rucaparib, pancreatic cancer patients with BRCA1/BRCA2 mutations showed response rates of 22% and 16%, respectively." (PMID 34771675, 2021). "Given we find mutated BRCA1/BRCA2 genes in a significant proportion of patients with familial pancreatic cancer, the utility of these PARPi have been explored in PDAC trials." (PMID 34771675, 2021). "On the other hand, removal of γH2A.X foci occurred with similar efficiency in BRCA2-proficient BxPC3 and BRCA2-deficient Capan-1 pancreatic cancer cells, resulting in similar DNA repair kinetics upon irradiation with X-ray photons." (PMID 32260562, 2020). "Homozygous mutations in FANCD1 (also known as BRCA2) lead to increased susceptibility to breast, ovarian, and pancreatic cancer." (PMID 32630050, 2020). "As shown in both ovarian and breast cancer, the POLO trial demonstrated the potential for PARP inhibition in pancreatic cancer, likely setting a new standard of care in patients presenting pancreatic cancer with germline BRCA1 or BRCA2 mutation." (PMID 32635552, 2020). "Mutations in BRCA1/2 and in Partner and Localizer of BRCA2 (PALB2) genes are reported in approximately 5% to 9% of pancreatic cancer patients." (PMID 32366019, 2020). "Pathogenic BRCA2 variants are associated with an increased risk of other cancers, including ovarian and pancreatic cancer identified as an important consideration for surveillance in the Kenyan patient who was eligible for return of research results." (PMID 32231682, 2020). "A family history of pancreatic cancer is an essential risk factor, and germline BRCA2 mutations comprise the highest proportion of known reasons for inherited pancreatic cancer." (PMID 32122376, 2020). "Germline mutations of the tumor suppressor gene BRCA2 are associated with a 3.5-fold increased risk of pancreatic cancer, and the gene is identified as the most common inheritable cause." (PMID 31963309, 2020). "A number of studies have shown that pedigrees with germline mutations in ATM, BRCA1, and BRCA2 also have an increased lifetime risk of pancreatic cancer in familial pancreatic cancer (FPC) kindreds." (PMID 31480737, 2019). "The benefits of PARP inhibitor-mediated synthetic lethality for those with germline BRCA1 or BRCA2 mutations are now undeniable and highlights the importance of germline testing for all patients with pancreatic cancer." (PMID 32030362, 2019).
pancreatic cancer (continued). "Overall, pathogenic BRCA1 and BRCA2 germline variants were observed in patients with expected malignancies such as breast, ovarian, prostate and pancreatic cancer, a large proportion of which showed loss of the wild-type allele in the tumor sample." (PMID 31263571, 2019). "In familial pancreatic cancer, BRCA2 is mutated in about 5% to 10% of cases and BRCA1 in approximately 1%." (PMID 31540286, 2019). "Leung and Saif described an example of two patients with BRCA2-associated pancreatic cancer treated with PARP inhibitors." (PMID 29777302, 2018). "Family studies have demonstrated that both BRCA1 and BRCA2 mutation carriers have an increased risk of developing pancreatic cancer." (PMID 29777302, 2018). "Adults with a pathogenic BRCA2 variant and at least two relatives with pancreatic cancer and all patients with Peutz-Jegher syndrome also meet high-risk criteria." (PMID 30186770, 2018). "In this study, more individuals with a family history of pancreatic cancer had a pathogenic BRCA2 variant, but more of those with a personal history of pancreatic cancer had a BRCA1 variant." (PMID 30186770, 2018). "In case of BRCA1 mutation carriers the relative risk for pancreatic cancer is 3.1 and 6.6 in relatives of BRCA2 mutations carriers." (PMID 29777302, 2018). "This is likely related to small sample size, but is an interesting observation as typically in larger cohorts, the risk of pancreas cancer is higher in the BRCA2 cohort." (PMID 30186770, 2018). "BRCA1 and BRCA2 are the most common of the known genetic mutations involved in familial pancreatic cancer." (PMID 29777302, 2018). "The exposure of BRCA2-deficient pancreatic cancer Capan-1 cells to the DNA damaging agent hydrogen peroxide (H2O2) induced large amounts of PAR formation in the cells." (PMID 27926532, 2017). "Together with their previous study, they estimated that BRCA2 mutations accounted for 6% of pancreatic cancers in high-risk families for pancreatic cancer and 6% of families fulfilled the criteria of familial pancreatic cancer." (PMID 29069866, 2017). "In one recent cohort study of over 300 patients with pancreatic cancer, pathologic germline mutations in BRCA2 were identified in 3.3%, BRCA1 mutations in 1.2%, and PALB2 in 0%." (PMID 28454122, 2017). "The most common single targetable alteration identified was a previously undetected BRCA2 mutations in pancreatic cancers." (PMID 28028924, 2017). "In pancreatic cancer, in vitro and in vivo data suggest that pancreatic cancers with BRCA2 mutations are more susceptible to DNA-crosslinking agents." (PMID 29069866, 2017). "Another case of a pancreatic cancer patient with a 6174delT BRCA2 mutation showed prolonged survival after docetaxel, capecitabine, and gemcitibine combination followed by single agent irinotecan, despite prognostically unfavorable disease." (PMID 28452926, 2017). "Three tag missense polymorphisms (rs1799966 on BRCA1; rs766173 and rs144848 on BRCA2) were genotyped in 603 pancreatic cancer patients in a Chinese population." (PMID 28415599, 2017). "Mutations of BRCA2 are found in approximately 7.3% of familial pancreatic cancer patients and show the increased risk by up to 20-fold." (PMID 28452926, 2017). "All these cases combined show that BRCA2 mutations can be used as predictive biomarkers for increased sensitivity of pancreatic tumors to DNA-intercalating agents." (PMID 28452926, 2017). "Inherited genetic factors account for approximately 5-10% of pancreatic cancer, and BRCA2 is the most common known germline mutation identified." (PMID 28454122, 2017). "It has been estimated that in the patient groups with familial pancreatic cancer, BRCA2 is the most common germline mutation, accounting for as many as 17% of FPC kindreds." (PMID 29069866, 2017).
pancreatic cancer (continued). "Mutated and thus frequently inactivated BRCA2 cause an increased risk of developing breast, ovarian, prostate, stomach, and pancreatic familial cancers." (PMID 28452926, 2017). "We have also evaluated the contribution of BRCA1/BRCA2 founder mutations in a consecutive series of pancreatic cancers diagnosed at a tertiary cancer center." (PMID 27532258, 2016). "Carriers of BRCA1 and BRCA2 mutations genes are at an increased risk for cancer at body sites other than breast, such as prostate, stomach, pancreatic cancers and melanoma." (PMID 27377827, 2016). "Mutations in BRCA2 confer a higher risk for developing cancers of the pancreas and male breast, and BRCA1 mutations seem to be predominantly associated with a higher risk for developing peritoneal and fallopian tube cancer." (PMID 27532258, 2016). "We have recently shown that germline mutations of BRCA1 and BRCA2 sensitize pancreatic cancers to treatment with cisplatin and gemcitabine." (PMID 28033382, 2016). "Since this mutation represents 55% of all BRCA2 germline mutations in our population, it can be estimated that the total contribution of mutations in this gene for pancreatic cancer is about 2.8%." (PMID 27532258, 2016). "BRCA2 germline mutations are the most frequent genetic alteration in familial pancreatic cancer and occur in 5–20% of the patients." (PMID 27630665, 2016). "Our study shows a high incidence of abnormal pancreatic imaging findings in patients with BRCA1/BRCA2 genetic mutations, including pancreatic atrophy, cysts, ductal dilation, and pancreatic cancer." (PMID 27069714, 2016). "It has been known that patients of hereditary breast and ovarian cancer syndrome (HBOC), caused by a germline mutation in BRCA1 or BRCA2, have an increased risk for breast, ovarian, prostate and pancreatic cancers." (PMID 26766567, 2016). "Although this supports previous expert recommendations from the “CAPS Consortium” to consider pancreatic cancer screening of BRCA2 mutation carriers with family history of the disease, it questions the methods and efficacy for such screening." (PMID 27069714, 2016). "A 49-year-old woman with advanced pancreatic cancer in the setting of BRCA2 mutation who was treated with mitomycin C and capecitabine after progressing through two previous regimens also achieved a partial response." (PMID 25714017, 2015). "Using simulation modeling techniques, we projected outcomes for hypothetical cohorts of BRCA2 mutation carriers, with varying numbers of first-degree relatives with a history of pancreatic cancer, that underwent MRI-based pancreatic screening strategies." (PMID 26844277, 2015). "Targeting defects in the DNA repair machinery of neoplastic cells, for example, those due to inactivating BRCA1 and/or BRCA2 mutations, has been used for developing new therapies in certain types of breast, ovarian and pancreatic cancers." (PMID 26511885, 2015). "Through analysis of the literature it was found that both BRCA1 and BRCA2 mutations are associated with the incidence of pancreatic cancer and that BRCA2 mutation poses an increased risk for developing pancreatic cancer." (PMID 26236408, 2015). "Breast, ovarian and pancreatic cancers with BRCA1 or BRCA2 mutations and/or signature 3 mutations show larger numbers of structural rearrangements than cases without, consistent with a deficiency in error-free double-strand break repair." (PMID 26511885, 2015). "It is clear that BRCA1/2 mutations are evident in many familial breast-pancreas cancer families and that carriers of the BRCA2 mutation have an increased risk of developing pancreatic cancer." (PMID 26236408, 2015). "BRCA2 mutation carriers are at higher risk of developing different types of cancers relative to the general population, including pancreatic cancer." (PMID 26844277, 2015). "BRCA2-deficient murine models of pancreatic cancer have been established in order to evaluate both diagnostic and therapeutic strategies for FPC." (PMID 24624093, 2014).
pancreatic cancer (continued). "Within high‐risk pancreatic cancer kindreds, inherited mutations in BRCA2 represent the most frequently encountered germline genetic alteration." (PMID 24268522, 2014). "This would include patients with FPC or carriers of a mutation in an established high-penetrance PDAC susceptibility gene (e.g., BRCA2 or PALB2) with at least one case of pancreatic cancer in a first-degree relative." (PMID 24624093, 2014). "So far, all described BRCA2 mutation-associated tumors of the pancreas showed the classical histomorphology of common ductal adenocarcinomas." (PMID 24959366, 2014). "As previously noted, BRCA2 mutation carriers far outnumber BRCA1 mutation carriers in both HBOC-associated pancreatic cancer and FPC." (PMID 24624093, 2014). "Murine pancreatic cancers emerging in Brca2Tr/F11 strains in which both Brca2 alleles are inactivated in PDX1‐CRE expressing cells exhibit a preponderance of acinar cell carcinoma histology." (PMID 24268522, 2014). "Here, we review recent studies that describe genetically engineered mouse models (GEMMs) for pancreatic cancer associated with BRCA2 mutations." (PMID 24268522, 2014). "The estimated risk of developing pancreatic carcinomas is increased 3.5–10-fold in carriers of BRCA2 mutations." (PMID 24959366, 2014). "Considering these two PALB2 variants as causal mutations, the prevalence of PALB2 mutation in our BRCA1/BRCA2 breast and pancreatic cancer series is 1.5% (2/132)." (PMID 23935836, 2013). "Patients with a BRCA2 mutation are ten times more likely to develop pancreatic cancer compared with the average risk population." (PMID 23202913, 2012). "In both sexes, BRCA2 deficiency increases the risk of developing cancers of the pancreas, stomach, gallbladder, and bile duct, as well as melanoma." (PMID 21750719, 2011). "BRCA2-deficient CAPAN1 pancreatic cancer cells were sensitive to highly active PARP inhibitors, while moderately active PARP inhibitors did not affect cell survival." (PMID 21819606, 2011). "This dataset will therefore prove useful in deciphering the genetic contribution to both BRCA2-deficient and pancreatic cancers." (PMID 21750719, 2011). "Germline BRCA2 gene mutations are responsible for ~10% of familial pancreatic cancer but mutations in this gene are also observed in approximately 7–10% of sporadic PDAC." (PMID 21512581, 2011). "PALB2 (Partner And Localizers of BRCA2) has been proven to cause breast and pancreatic hereditary cancer." (PMID 21819606, 2011). "This study estimated pancreatic cancer risk in BRCA2 carriers by age 70 years to be 2.1% (95% CI 1.2–3.0%) in men, and 1.5% (95% CI 0.9–2.1%) in women, reflecting a combined RR of 3.51 (95% CI 1.87–6.58)." (PMID 17213823, 2007). "Germline BRCA2 mutations predispose to ovarian, breast and pancreatic cancer, while a germline MRE11 mutation is associated with an ataxia telangiectasia-like disorder." (PMID 16417627, 2006). "We conclude that the rate of the predominant Jewish BRCA2 mutation in patients with gastric and pancreatic cancer significantly differ from that of the general population of the same ethnic origin." (PMID 11207041, 2001). "Moreover, the presence of BRCA1 and BRCA2 mutations in PCa patients increased the risk of developing other tumors, such as male breast cancer, cancer of the pancreas, and melanoma, as compared with the incidence in the general population." (PMID 41590381, 2026). "Furthermore, in cases of TNBC with BRCA1 mutation and pancreatic cancer with BRCA2/PALB2 germline alterations, a more abundant macrophage population, encompassing M1 and M2 subtypes, is evident." (PMID 40830526, 2025). "In addition, cancer cells were isolated from mice and then tested for sensitivity to chemotherapeutic agents, demonstrating that BRCA2-deficient pancreatic tumors exhibit increased sensitivity to cisplatin and PARP inhibitors." (PMID 41155399, 2025).
pancreatic cancer (continued). "Highly penetrant variants of the APC and BRCA2 genes were also implicated in several rare variant association studies in pancreatic cancer patient families, indicating that they could be potential targets for new associations." (PMID 39858023, 2025). "Pancreatic cancer patients with BRCA1/BRCA2 mutations are uniquely positioned to benefit from platinum-based chemotherapies (PtCh) like FOLFIRINOX due to their tumors' defective homologous recombination repair (HRR) mechanisms, which leave them vulnerable to DNA-damaging agents." (PMID 41466916, 2025). "BRCA gene mutations have been shown in two meta-analyses to be associated with a high increased risk of pancreatic cancer (RR 2.65; 95% CI 1.43–4.91), with an indication this risk is higher in BRCA2 (RR 5.12; 95% CI 3.17–8.27) than in BRCA1 (RR 1.71; 95% CI 1.16–2.52) mutations." (PMID 40584837, 2025). "Another participant (arm B) developed pancreatic cancer (arm B, BRCA2 mutation carrier)." (PMID 41193417, 2025). "While inhibitors of PARP have been approved for BRCA-mutated cancers, exploiting synthetic lethality in DNA repair pathways, only 5-10% of pancreatic cancer patients possess BRCA1 or BRCA2 mutations, limiting the applicability of PARP inhibitors in pancreatic cancer treatment." (PMID 39528473, 2024). "The methylation status of BRCA2 was associated with low-grade pancreatic cancer (p=0." (PMID 38577595, 2024). "However, only 5-10% of pancreatic cancer patients have germline or somatic mutations in the BRCA1 or BRCA2 genes, which limits the application of therapies involving PARP1." (PMID 39528473, 2024). "BRCA2 promoter methylation was associated with low-grade pancreatic cancer (p=0.023)." (PMID 38577595, 2024). "The most prevalent pancreatic cancer germline abnormalities observed involve variants in BRCA2." (PMID 38732320, 2024). "The methylation status of BRCA2 was associated only with low-grade pancreatic cancer (p=0." (PMID 38577595, 2024). "Finally, although mutations in homologous genes BRCA1/BRCA2 increase the risk of pancreatic cancer, they also appear to be associated with better neoadjuvant efficacy, but such data is not committed in the SEER database." (PMID 38665957, 2024). "Interestingly, BRCA2 showed a strong risk association with pathogenic variants and prostate and pancreatic cancer." (PMID 38397209, 2024). "CAPS recommends pancreatic cancer screening beginning at the age of 50 years or 5 years earlier than for high-risk individuals with defined familial pancreatic cancer in patients with BRCA2, ATM, and PALB2 mutations (Grade 2: probably do it)." (PMID 39200847, 2024). "However, it was revealed that pancreas cancer with BRCA2 p.I3169M fs*48 variant is practically sensitive to both platinum and PARP inhibitors in our case." (PMID 37956396, 2024). "Carriers of BRCA2 mutations face a lifetime risk of pancreatic cancer ranging from 5% to 10%." (PMID 38809921, 2024). "Taken together, these findings suggest that inheritable mutations in multiple genes involved in DNA damage repair and genome stability maintenance lead to a higher risk of developing pancreatic cancer, with BRCA2 being the most commonly mutated gene compared to others in FPC." (PMID 39595558, 2024). "Another study reported that the 617delT BRCA2 mutation could prolong survival after chemotherapy in a patient with advanced pancreatic cancer, despite the unfavorable prognosis." (PMID 37304241, 2023). "Taken together, these studies suggest that BRCA1/BRCA2 mutations may serve as good predictive biomarkers for the response of pancreatic tumors to chemotherapeutic agents related to DNA damage." (PMID 37304241, 2023). "Although pancreatic cancer risks were not shown to be significantly elevated in female relatives of BRCA1 or BRCA2 carriers, a trend toward risk for pancreatic cancer was still observed for female relatives of BRCA2 carriers (RR 2.54, 95% CI 1.02-6.30; P = 0.055)." (PMID 36861435, 2023).